HGF (hepatocyte growth factor)
Diseases named in the same sentence as HGF in open-access papers (continued):
Sharing a sentence is not in itself a finding about the gene and the disease.
breast carcinoma (continued). "Our study provides further evidence that a pro-oxidative environment is involved in activating and sustaining the oncogenic HGF/c-Met signaling and that re-expressing EcSOD in breast cancer cells inhibits HGF-stimulated oncogenesis." (PMID 29296173, 2017). "We first stimulated 3D growth of MDA-MB231 with rHGF and observed that MnTE treatment inhibited the induction of breast cancer cell growth and stellate formation by HGF." (PMID 29296173, 2017). "Correspondingly, previous reports showed that the circulating HGF value was decreased after tumor resection in lung and breast cancer, and was parallel with tumor response in SCLC." (PMID 29069748, 2017). "Although over twenty adipokines are known; only twelve (adiponectin, leptin, IL-6, TNF-α, HGF, PAI–1, resistin, secreted frizzled-related protein 5 (SFRP-5), lipocalin 2, IL-8, apelin and visfatin) have been implicated in breast cancer." (PMID 29088874, 2017). "The regulatory relationship between miR-7 and HGF was also investigated by examining the expression of HGF and miR-7 in 41 pairs of breast cancer and normal tissues." (PMID 29133945, 2017). "In the past years, mountains of clinical studies have described c-Met overexpression and pathway hyperactivation in tissues of breast cancer patients, and found a strong relationship between high HGF/Met signaling and tumor progression." (PMID 28915628, 2017). "To further provide evidence that ROS contributes to HGF-mediated oncogenic stimulation, we treated breast cancer cells with an SOD mimetic, MnTE-2-PyP (MnTE)." (PMID 29296173, 2017). "High levels of HGF also correlate with lymph node metastasis and relapse in breast cancer patients, multiple myeloma patients and myeloid leukemia patients." (PMID 28420162, 2017). "To determine the regulation of HGF-stimulated tumorigenesis by ROS, we utilized an orthotopic mammary tumor model." (PMID 29296173, 2017). "Compared to MMTV‐Her‐2 transgenic mouse mammary tumors, H1047R tumors showed increased upregulation of Wnt/β‐catenin/Axin2, hepatocyte growth factor (Hgf)/Stat3, insulin‐like growth factor 2 (Igf‐2), and Igf‐1R pathways." (PMID 28296140, 2017). "Previous studies have shown that microenvironments including transforming growth factor-β (TGF-β) and hepatocyte growth factor (HGF) have roles in the plasticity of breast cancer cells and colon cancer cells, respectively." (PMID 27418136, 2016). "We found that, consistently with the results of studies of hepatocyte growth factor (HGF) in breast cancer, Src and PYK2 activation also occurred downstream of the IL-17E receptor in TNBC cells." (PMID 27462789, 2016). "In breast cancer, activation of HGF/MET/PI3K pathway drives tumor formation, metastasis, and drug resistance because of the crosstalk between MET and other oncogenic pathways." (PMID 26716644, 2016). "Given the precedent for the role of HGF signaling in invasive breast cancer, a better understanding of HGF’s role in BBC tumorigenesis was necessary." (PMID 27057482, 2016). "Breast CAFs expressed higher levels of HGF compared to normal fibroblasts, and deprivation of HGF reduced CAF-mediated colony formation of human breast cancer cells." (PMID 26828520, 2016). "In MCF7 and T47D breast cancer cells, c-Met upregulation accompanied resistance to fulvestrant, facilitating stimulation by HGF/SF-secreting stromal fibroblasts." (PMID 26828520, 2016). "Hepatocyte growth factor (HGF) and its receptor, C-Met (an oncogene), are both critical mediators of breast cancer progression and are highly expressed in these tissues." (PMID 27472371, 2016). "FGFs, HGF, TGF-β and SDF-1 are reported to be produced by breast cancer-associated fibroblasts and promote tumor proliferation." (PMID 26828520, 2016). "In this study, MDA-MB-231, MCF-7, and BT-474 human breast cancer cells were chosen to assess the effect of HVS on HGF-induced c-Met phosphorylation using Western blot analysis, to confirm the initial biochemical assay results." (PMID 27086914, 2016).
breast carcinoma (continued). "In summary, we show that Met and HGF have a multi-factorial relationship to the biology and outcome of breast cancer, influenced by gene copy number and protein expression, activation status, stromal environment, and cellular localisation." (PMID 27175600, 2016). "For example, HGF expression was able to overcome lapatinib-sensitivity in several HER2-dependent breast cancer cell lines." (PMID 27655711, 2016). "Overexpression and increased gene copy numbers of HGF and MET in tumor tissues were associated with the resistance to and failure of trastuzumab treatment in HER2-postive breast cancer." (PMID 26716644, 2016). "When normal fibroblasts were co-cultured with MDA-MB-468 breast cancer cells, HGF secretion increased colony formation and tumor growth in a mouse model." (PMID 26828520, 2016). "The results of this study showed that HVS treatment caused a marked dose-dependent inhibitory effect on HGF-induced migration and invasion of MDA-MB-231 breast cancer cells." (PMID 27086914, 2016). "Results demonstrated the ability of HVS treatment to significantly inhibit HGF-induced proliferation across a broad spectrum of c-Met expressing human breast cancer cell lines in a dose-responsive manner." (PMID 27086914, 2016). "Apparently, HVS treatment significantly suppressed HGF-induced mammary tumor cell migration in a dose-dependent manner, with an IC50 value of 2.5 μM, demonstrating three-fold improvement versus its parent (−)-oleocanthal (IC50 8.5 μM)." (PMID 27086914, 2016). "In invasive and metastatic MTLn3 breast carcinoma cells, HGF stimulated both initial adhesion to and motility on the ECM ligands laminin 1, type I collagen, and fibronectin, and induced rapid tyrosine phosphorylation and activation of both c-MET and FAK." (PMID 28536400, 2015). "HGF is a poor prognostic factor of patients with various types of cancer, including hepatocellular carcinoma and breast cancer." (PMID 25436000, 2015). "The next big challenge will be to determine the circumstances under which luminal progenitor cells stimulated by HGF can give rise to breast cancers." (PMID 26165517, 2015). "Several lines of evidence suggest that HGF-dependent c-Met signalling (both paracrine and autocrine) is an important mediator of breast cancer progression." (PMID 25887320, 2015). "Hyper-activation of the HGF-Met pathway correlates with aggressiveness and poor prognosis of diverse carcinomas including breast cancers." (PMID 25946048, 2015). "Multiple studies have demonstrated that HGF is overexpressed in breast cancer stroma, and binds to c-Met receptors expressed on epithelial cells to regulate cancer progression." (PMID 26252654, 2015). "Recently, strong evidence supports the role for the hepatocyte growth factor (HGF) and its receptor, c-Met, in the development and progression of breast carcinoma." (PMID 25580621, 2015). "Elevation of HGF protein levels, both intratumoural and systemic, has been noted in many tumour types, such as lung cancer (50%), breast cancer (91%), stomach cancer (87%), colon cancer (95%), cancer of the head and neck (45%) and liver cancer (33%)." (PMID 28943627, 2015). "Other mutations within c-MET’s juxtamembrane region or its Sema domain, where HGF binds, have also been noted in gastric cancer, breast cancer, pleural mesothelioma, and small-cell lung cancer." (PMID 28943627, 2015). "A crosstalk between human adipose-derived mesenchymal stem cells (ADSCs) and breast cancer cells mediated by HGF/c-MET signaling has been reported to enhance tumor cells migration, acquiring a metastatic signature, and sustained tumor self-renewal." (PMID 28536400, 2015). "Results of this study demonstrated that the marine-derived araguspongine C treatment inhibited HGF-induced growth and proliferation of multiple breast cancer cell lines in vitro." (PMID 25580621, 2015). "HGF has been shown to trans-activate epidermal growth factor receptor (EGFR) in PyVmT mouse mammary carcinoma cells." (PMID 25887320, 2015).
breast carcinoma (continued). "It has also been shown that HGF protects MDA-MB-453 breast cancer cells from adriamycin-induced apoptosis." (PMID 25887320, 2015). "In support of this data, mammary gland specific overexpression of HGF (the ligand for c-Met) in transgenic mice induces mammary hyperplasia that progressed to form invasive mammary tumors compared to wild type mice." (PMID 25938541, 2015). "Ribozyme transgenes targeting of HGF in human fibroblasts or c-met in MDA-MB-231 tumor cells resulted in a reduction of mammary cancer cells in vitro invasiveness." (PMID 25880005, 2015). "HGF at a concentration of 40 ng/ml was used in growth studies as it showed maximum growth induction in the three human breast cancer cell lines investigated." (PMID 24849787, 2014). "A similar nuclear localization of the receptor of HGF c-Met has been reported in breast cancer cells, where such overexpression was related to increased metastatic potential and aggressive disease." (PMID 24988459, 2014). "If DATE becomes shortened by at least five adenosines, the element loses its repressive effect resulting in HGF expression in breast tissue and breast cancer cells." (PMID 24716444, 2014). "SOCS7 loss has resulted in the amplification of HGF/C-MET growth and migrational signalling in the two studied breast cancer cell lines, but pharmacological blockade of PLCγ-1 enzymatic activity has mitigated this amplified signalling." (PMID 25162020, 2014). "The prognosis of other cancer types such as non-small cell lung cancer, colorectal cancer, ovarian cancer, breast cancer were also reported associated with the high levels of MET and/or HGF expression." (PMID 24416238, 2014). "Our findings revealed a master role for HGF/c-Met crosstalk in mediating a tumorigenic role of ASCs in breast cancer, making c-Met a good target for developing new cancer therapies." (PMID 24327602, 2014). "Future research aims to evaluate the role of obesity and the HGF/c-Met pathway in basal-like breast cancer progression." (PMID 25072025, 2014). "We found both ASC-specific or breast cancer cells–specific diffusible factors changed their expression after co-culture, however only HGF expression significantly correlated with the ability of ASCs to influence tumorigenic behaviour of epithelial." (PMID 24327602, 2014). "Results of the present study demonstrated that (-)-oleocanthal treatment suppressed HGF-stimulated growth of human breast cancer cell lines MDA-MB-231, MCF-7 and BT-474 cells in dose- and time-dependent manners." (PMID 24849787, 2014). "Noticeably, those epithelial breast cancer cells, whose behaviour remained unchanged in presence of ASCs, displayed HGF levels similar to control cells." (PMID 24327602, 2014). "Earlier studies have shown HGF to act as a motogen or morphogen in most breast carcinoma cell lines." (PMID 24849787, 2014). "Pharmacological c-Met inhibition showed that a HGF/c-Met crosstalk between ASCs and breast cancer cells enhanced tumor cells migration, acquiring a metastatic signature, and sustained tumor self-renewal." (PMID 24327602, 2014). "Implication of beta-catenin to mediate HGF/c-Met signals was further confirmed by beta-catenin mislocation in xenografts generated after co-injection of breast cancer cells, KBr1 and KBr2, with ASCs." (PMID 24327602, 2014). "We previously showed that DGKα is necessary for matrix invasion promoted by Epidermal Growth Factor (EGF) or Hepatocyte Growth Factor (HGF) in MDA-MB-231 breast carcinoma cells." (PMID 24887021, 2014). "The same mechanism has been proposed in metastatic breast cancer where HGF/c-Met axis is exploited to counteract the functional consequences of hypoxia." (PMID 24952592, 2014). "Together these data support a role for HGF/C-MET/PLCγ-1 route as a direct mediator in breast cancer progression, thus making it a good target for therapeutic intervention." (PMID 25162020, 2014).
breast carcinoma (continued). "A recent report shows that HGF signaling from normal mammary fibroblasts is able to promote basal-like breast cancer phenotypes in a 3D culture model." (PMID 24816718, 2014). "Here we investigated the interplay between HGF/SF-Met and Ras signaling in the tumor metabolism and motility of a breast cancer cell line in vitro as well as on tumor growth and blood flow in vivo." (PMID 25593982, 2014). "Immunoblot analyses were performed on extracts from neuTEMT, CL2 cells and the MDA-MB-231 human breast cancer cell line to examine the cross-talk between HGF/c-Met and mTORC1 signaling." (PMID 24927123, 2014). "Our data pointed out to a crosstalk between ASCs and breast cancer cells mediated by HGF/c-Met signaling." (PMID 24327602, 2014). "Further results showed that (-)-oleocanthal treatment caused a marked dose-dependent inhibitory effect on HGF-induced migration and invasion of MDA-MB-231 breast cancer cells in vitro." (PMID 24849787, 2014). "Noticeably, inhibiting c-Met kinase we were able to interfere with migratory activity and acquisition of metastatic signature of co-cultured breast cancer cells, and significantly reduce HGF expression, as well." (PMID 24327602, 2014). "In this study, MDA-MB-231, MCF-7, and BT-474 human breast cancer cells were used to assess the effect of (-)-oleocanthal on HGF-induced c-Met phosphorylation (activation)." (PMID 24849787, 2014). "The results of this study showed that activation of the HGF/c-Met signaling pathway in MDA-MB-231 mammary cancer cells resulted in the activation of downstream effectors Akt and MAPK." (PMID 24849787, 2014). "Recently, HGF serum levels were reported to be significantly elevated with increasing tumor stage in breast cancer patients, raising the possibility of alternate sites of HGF production." (PMID 24156623, 2013). "We have previously shown the involvement of the HGF/MET system in tumor-bone interaction contributing to human breast cancer metastasis." (PMID 24260160, 2013). "For example, conditioned medium of breast cancer cells enhances HGF production in fibroblasts, along with a raise in prostaglandin-E2." (PMID 23296269, 2013). "The resulting experimental data, together with patient data, suggest an important role for hepatocyte growth factor (HGF) signaling in premalignant to invasive basal-like breast cancer." (PMID 24025166, 2013). "We have previously shown the involvement of the receptor tyrosine kinase MET and its ligand HGF (also known as scatter factor, HGF/SF) in tumor-bone interaction contributing to human breast cancer bone metastases." (PMID 24260160, 2013). "HGF regulates multiple cellular processes that stimulate cell proliferation, invasion, and angiogenesis, both in the normal mammary gland and in breast cancer." (PMID 24156623, 2013). "HGF is generally produced locally within the mammary gland/mammary cancer and acts in a paracrine manner." (PMID 24156623, 2013). "High level of HGF/c-Met expression is considered as a possible indicator of metastasis, earlier recurrence and shortened survival in breast cancer patients." (PMID 22242160, 2012). "Collectively, these data suggested that HGF enhanced the metastasis of breast cancer xenografts to the lung and liver." (PMID 22242160, 2012). "In the context of breast cancer, fibroblasts are a major component of the stroma and have been shown to express HGF." (PMID 22788954, 2012). "The functional importance of HGF-induced PKCζ activation in breast cancer metastasis was further demonstrated in a xenograft experiment in which the suppression of PKCζ abrogates HGF-induced metastasis of breast cancer to the lung and liver." (PMID 22242160, 2012). "The Met ligand HGF can promote invasiveness of HER2-expressing breast cancer cells through a MEK-dependent mechanism that results in reduced E-cadherin and internalization of ZO-1, indicative of basement membrane breakdown and EMT." (PMID 23227361, 2012).
breast carcinoma (continued). "We argue that this "wave" is induced by specific signal transduction; it is induced by HGF/SF, and reduced by Met-inhibition in breast cancer cells." (PMID 22970283, 2012). "In this communication, we show that, in addition to producing HGF for cancer cell growth, NAFs co-cultured with breast cancer cells also secreted ADAMTS1 for cancer cell invasion." (PMID 22514714, 2012). "When the c-Met+ and CXCR4+ cell counts in breast cancer were calculated according to the clinicopathology of these patients, the numbers of HGF+, c-Met+ or CXCR4+ cells increased along with the histopathological grading of the tumor (P<0.001)." (PMID 22242160, 2012). "Met-inhibition experiments demonstrating inhibition of cell motility, validated the important role of HGF/SF-induced Met activation in breast cancer metastasis." (PMID 22970283, 2012). "MCF7 breast cancer cell line expresses low levels of Met and although HGF/SF induced a 1.86 fold increase in Met phosphorylation, its levels are significantly lower than in MDA231 cells, by a factor of 6.4." (PMID 23049908, 2012). "To determine the signaling pathways leading from Met activation to metastasis and poor prognosis, we measured the kinetic gene alterations in breast cancer cell lines in response to HGF/SF." (PMID 23049908, 2012). "To further examine the effects of HGF-induced CXCR4 expression via PKCζ on breast cancer invasion and metastasis in vivo, we inoculated the mammary fat pads of athymic nude mice with MDA-MB-436 cells." (PMID 22242160, 2012). "Here we demonstrate that treatment of breast cancer cells sensitive to EGFR TKIs with recombinant HGF confers a resistance to EGFR TKIs." (PMID 22788954, 2012). "We demonstrated that in breast cancer cells, PKCζ was directly stimulated by HGF-activated signaling." (PMID 22242160, 2012). "Recent findings indicate that ezrin is required for metastasis of breast carcinoma, osteosarcoma and HGF-induced rhabdomyosarcoma." (PMID 22629406, 2012). "Consistently, we found that HGF expression level was extremely low in breast cancer MDA-MB-468 cells compared to CAFs and NAFs." (PMID 21249190, 2011). "This endothelial-induced EMT is at least partially facilitated by HGF making this a potential novel therapeutic target for patients with the basal-like subtype of breast cancer." (PMID 21915264, 2011). "Using HGF as a common marker, it appeared that pre-coculture with the breast cancer MDA-MB-468 cells increased and maintained higher HGF protein levels in NAF #200N.E3 and E4." (PMID 21249190, 2011). "Co-culture with human breast cancer MDA-MB-468 cells in a transwell system enhanced NAFs to secret HGF as well as promote tumorigenecity." (PMID 21249190, 2011). "Deprivation of HGF using a neutralizing antibody reduced CAF-mediated colony formation of human breast cancer cells, indicating that CAFs enhanced cancer cell colony formation mainly through HGF secretion." (PMID 21249190, 2011). "Nanoparticle-encapsulated EGCG retained its biological activity and blocked hepatocyte growth factor (HGF)-induced intracellular signaling in the breast cancer cell line MBA-MD-231 as potently as free EGCG." (PMID 24213123, 2011). "SPINT2 (Hepatocyte growth factor activation inhibitor-2, HAI-2) is capable of regulating a HGF-induced invasion of human breast cancer cells." (PMID 21347235, 2011). "Conversely, deprivation of HGF using a neutralizing antibody reduced CAF-mediated colony formation of breast cancer cells, indicating that CAFs enhanced cancer cell colony formation mainly through HGF." (PMID 21249190, 2011). "Co-culturing NAFs with breast cancer cells in a transwell system for several passages was able to enhance the ability of NAFs to promote tumorigenicity as well as HGF expression to the compatible level as that of CAFs." (PMID 21249190, 2011).